TNF (tumor necrosis factor)
Diseases named in the same sentence as TNF in open-access papers (continued):
Sharing a sentence is not in itself a finding about the gene and the disease.
Hypertension (continued). "The observed reduction in blood pressure upon TNF‐α blockade underscores the potential benefits of additional anti‐inflammatory therapies for individuals in the highest quartile of blood pressure, ultimately mitigating hypertension‐mediated organ damage." (PMID 38504425, 2024). "We hypothesized that a high-salt diet may increase serum levels of IL-6, IL-8, TNF-α, and Ang II to promote hypertension." (PMID 36925479, 2023). "Moreover, atorvastatin has a beneficial impact on endothelial function and inflammation, which is reflected by decreased serum levels of ICAM-1 and TNF-α levels in hypertension." (PMID 37759223, 2023). "Detection of higher TNF-α levels in HVs with DM, hypertension and hyperlipidemia on the other hand, proved these risk factors as the generators of TNF-α in the absence of an overt ischemic injury." (PMID 36056287, 2023). "In the regulation of apoptosis, exercise training downregulated the proapoptotic protein in hypertension by decreasing the upstream regulation of apoptosis such as the Fas ligand, TNF, TNF receptor 1, and FADD, and the downstream regulation of apoptosis such as t-Bid, Bad, Bak, and Bax." (PMID 37187789, 2023). "In the present study, TNF-α was significantly associated with G allele (both GG and GC genotype) and contributed to reduced BRS, which suggests the importance of retrograde inflammation in the onset of hypertension." (PMID 37838749, 2023). "This study comprehensively evaluated the changes of inflammation caused by high-salt diet in rats from the aspects of inflammatory cytokines (TNF-α, IL-8, IL-1β, and IL-6) and hormones related to hypertension (NE, LEP, and Ang II), and Vascular and renal lesions were also examined." (PMID 36925479, 2023). "These cells have a low activation threshold, produce TNFα and IFNγ and may contribute to vascular dysfunction and hypertension, which is recorded both during the COVID-19 disease and directly after vaccination." (PMID 38137381, 2023). "Prolonged hypertension leads to the systemic release of cytokines, including interleukin 17, interferon gamma, tumor necrosis factor-α, and interleukin 6, which contribute to renal fibrosis, alter sodium membrane transportation, and increase oxidative stress and arterial stiffness." (PMID 37842465, 2023). "Furthermore, monocyte-derived derived DCs from hypertensive mice produce increased amounts of ROS, IL-1β, TNF-α, IL-6, and IL-23 to promote hypertension and end-organ damage." (PMID 37266014, 2023). "Hypertension in pregnancy and childbirth all lead to increased maternal TNF-α and IL-6 levels." (PMID 37312032, 2023). "While butyrate and TNFα are both linked with hypertension, studies have not yet addressed their interaction in the colon." (PMID 36830627, 2023). "In addition, some studies have found that people with hypertension have elevated levels of circulating inflammatory cytokines, including IL-6, IL-1β, and TNF-α." (PMID 36937901, 2023). "Inflammation is an important factor in the pathogenesis of hypertension, therefore we used TNF, a proinflammatory cytokine, to determine whether B1R blockade prevents inflammation-induced B1R expression and oxidative stress." (PMID 36671012, 2023). "Furthermore, the preconditioning of mice with NS1619 prevented post-ischemic increases in intestinal TNF-α levels, and in vascular smooth muscle cells, BK channel activity promotes vasodilation and prevents arterial hypertension." (PMID 36835507, 2023). "Furthermore, similar results were obtained in Dahl Salt-Sensitive (SS) rats during a 5-week HS intake, which led to hypertension, as well as increased mRNA levels of TNF-α, IL-6, and IL-1β." (PMID 37108475, 2023). "Th1 and Th17 cells release pro-inflammatory cytokines, such as IFN-γ, TNF-α, and IL-17a, which are prominent pathogens in hypertension models while Treg cell inhibits Ang II-induced hypertension by releasing anti-inflammatory cytokines, which mainly include IL-10 and TGF-β." (PMID 36457803, 2022).
Hypertension (continued). "Recent animal studies have shown that hypertension is associated with elevated plasma levels of proinflammatory cytokines, such as C-reactive protein (CRP), interleukin (IL)-6, IL-1β, and tumor necrosis factor (TNF)-α." (PMID 35445013, 2022). "Moreover, GT supplementation (4 g/kg diet, 42 d) significantly reduced the concentration of TNF-α (a critical pro-inflammatory cytokine) in the serum of NaCl-induced hypertensive rats and enhanced the body’s total antioxidant status." (PMID 35600813, 2022). "The peptide decreased the protein expression of pro-inflammatory Toll-like receptor 4, phosphor-nuclear factor κB, phosphor-p38 MAPK, tumor necrosis factor (TNF) and interleukin (IL)-6 during hypertension-induced cardiac inflammation in SHR and high-fat diet-induced inflammation in SAMP8 mice." (PMID 35744990, 2022). "The TNF signaling pathway is an important inflammatory signaling pathway, and the study has showed that TNF-α may mediate vascular damage in hypertension by inhibiting endothelial cells." (PMID 35360657, 2022). "Ang II also failed to cause hypertension and cardiac hypertrophy in tumor necrosis factor-alpha (TNF-α) knockout mice." (PMID 36359731, 2022). "Associations between hypertension with TNF-α, IL-6, and CRP have been reported, suggesting that inflammation may link cataract and hypertension." (PMID 35565652, 2022). "Recent studies have shown that interleukin-1beta, interleukin-6, and TNF- alpha are all elevated in high blood pressure, suggesting that these inflammatory markers may play a role in the pathogenesis of hypertension." (PMID 36164390, 2022). "The EWH supplementation in DOCA-salt rats, when the hypertension was stabilized, restored the mitochondrial and cellular ROS production, NF-kB activation, and TNFα pro-inflammatory levels, improving the eNOS expression and endothelial function in MRA and aorta and reducing blood pressure levels." (PMID 36139783, 2022). "Furthermore, the inflammation is characterized by increased levels of local inflammatory cytokines such as TNF, IL10, and PTGS2, which are more likely to be useful diagnostic tools for hypertension in the future." (PMID 35308213, 2022). "Magnesium acts as an allosteric activator for adenylate cyclase, Na/K-ATPase, and phospholipase C. Magnesium downregulates IL-1 alpha, IL-4, IL-6, IL-1 beta, Il-10, IL-12, TNF-alpha and several chemokines involved in hypertension, numerous immune-inflammatory pathways, and in adverse pregnancies." (PMID 38807919, 2022). "This is probably related to the high levels of TNF-α observed during hypertension." (PMID 35185598, 2021). "As hypertension generally raises TNF-α, IL-1β, IL-6, HIF-1α, TGF-β, and VEGF mRNA expression and/or protein levels, the results obtained in the studied model may provide a positive prognostic factor for such activity in vivo." (PMID 33652665, 2021). "Irbesartan also increased the expression of IL-10 and inhibited the expression of TNF-α in the culture supernatants of monocytes from hypertensive patients with LVH in a concentration-dependent manner; of these groups, the 10–6 mol/L group exhibited the most significant changes." (PMID 33879070, 2021). "Since it is known that hypertension generally raises TNF-α, IL-1β, IL-6, HIF-1α, TGF-β, and VEGF mRNA and/or protein levels, the results obtained in the study may provide a positive prognostic factor for such activity in vivo." (PMID 33652665, 2021). "TNFα has been reported to lead to the development of hypertension in various hypertensive models." (PMID 33532132, 2021). "Interleukin‐5 (IL‐5), IL‐6 and IL‐12 levels correlated with mean CT in acute CSC (p = 0.008, p = 0.003 and p = 0.044, respectively), while IL‐8, IL‐6 and TNF‐α plasma levels correlated with hypertension in chronic CSC (p = 0.005, p = 0.033 and p = 0.001, respectively)." (PMID 32701204, 2021).
Hypertension (continued). "The generalized linear model adjusting for age, gender, and MAP further confirmed the substantial increase in TIFA protein expression and plasma levels of IL-1β and TNF-α in the order of healthy controls, systemic hypertension, idiopathic PAH, and CTD-PAH patients." (PMID 34238983, 2021). "However, it is reasonable to postulate that such decreases in renal levels of TNF‐α and other pro‐inflammatory cytokines facilitate sodium retention leading to the induction of hypertension in response to the intake of HS diet." (PMID 33345460, 2021). "Thus, further comprehensive studies would be required to examine the critical role of TNF‐α and its receptor activity in this non‐dipping pattern in hypertension induced by chronic AngII treatment and HS intake." (PMID 34427402, 2021). "Irbesartan also increased the expression of IL-10 and inhibited the expression of TNF-α in the culture supernatants of monocyte from hypertensive patients with LVH in a concentration-dependent manner; of these groups, the 10−6 mol/L group exhibited the most significant differences (P < 0.01)." (PMID 33879070, 2021). "In antiobesity/hypertension mechanisms played by metformin, the key molecular pathways, including TNF signaling pathway, NOD-like receptor signaling pathway, cytokine-cytokine receptor interaction, AMPK signaling pathway, FoxO signaling pathway, Jak-STAT signaling pathway, were revealed in details." (PMID 34334083, 2021). "Likewise, studies report a correlation between cytokines such as IL-6, TNFα, and C-reactive protein and blood pressure in patients with essential hypertension." (PMID 33953971, 2021). "Clinical studies have shown an association between hypertension and the circulating levels of fibroblast growth factor 21 (FGF21), tumour necrosis factor superfamily member 14 (TNFSF14) and tumour necrosis factor-α (TNF-α)." (PMID 32858953, 2020). "Other studies suggest that TNFα may participate in the regulation of blood pressure and target organ damage in hypertension." (PMID 32190663, 2020). "Based on these results, we speculated that PGRN, as a competitive molecule of TNF-α, is highly expressed in hypertension secondary to the increased inflammatory cytokines, particularly, TNF-α." (PMID 32424472, 2020). "However, the product of IFNγ and TNFα positively associated with NCB in models adjusted for age, sex, hypertension, hyperlipidaemia, waist: hip ratio, statin use as well as individual IFNγ and TNFα levels (β = 0.28, p < 0.001)." (PMID 32646751, 2020). "Furthermore, central pharmacological blockade or genetic knockout of TNF-α has been shown to prevent cardiac hypertrophy and to lower BP in animals with hypertension induced by ANG II through mechanisms similar to that of central blockade of NF-κB." (PMID 32760236, 2020). "However, there were few animal studies to address the role of anti-TNFα therapies in vascular dysfunction in hypertension." (PMID 32190663, 2020). "High TNF-α levels depict the presence of low-grade inflammation in hypertension." (PMID 32424472, 2020). "Tumor necrosis factor-α (TNF-α) plays a vital role in the pathogenesis of hypertension." (PMID 31666827, 2019). "Furthermore, hypertension was associated with a higher percentage of CD8+ T cells producing both IFN-γ and TNF-α." (PMID 31321561, 2019). "Treatment with TNF-a inhibitors is suggested to improve hypertension through an endothelium-dependent mechanism, which could indicate a contribution of increasing IGF1 levels." (PMID 31327319, 2019). "IFN‐γ has been shown to enhance NADPH oxidase activity in macrophages and TNF‐α can stimulate superoxide production by vascular smooth muscle cells, thus could worsen hypertension via several related mechanisms." (PMID 30414380, 2019). "In addition, it was found that level of TNF-α in plasma of hypertension patients was significantly higher." (PMID 31341840, 2019).
Hypertension (continued). "Several studies using female NZB/WF1 mice, a spontaneous model of SLE that mimics human disease and develops hypertension, have demonstrated that multiple factors contribute to the pathogenesis of hypertension, including inflammatory cytokines, tumor necrosis factor (TNF)-α, and oxidative stress." (PMID 31694260, 2019). "In Ang II–dependent hypertension, there is an imbalance between Th17/Treg in the spleen and in renal/cardiac infiltrating lymphocytes resulting in increased expressions of IL-17A, IL-23, and TNF-α, and decreased expression of IL-10." (PMID 31321561, 2019). "Hypertension is associated with the infiltration of immune cells into the adventitia and periadventitial fat, as well as the activation of T cells that release proinflammatory cytokines such as interleukin (IL)-17a, interferon (IFN)-γ, and TNF-α." (PMID 31694260, 2019). "In the colon, however, baicalin treatment counteracts hypertension-associated increases in the expression of Tlr2, TNF-α, IL-1β, and IL-23 but not HMGB1 in the SHRs." (PMID 31719823, 2019). "The increased adipose tissue mass causes a state of metabolic inflammation with high production of pro-inflammatory mediators, such as tumor necrosis factor (TNF-α), interleukins (e.g., IL-6, IL-8, IL-1β), and angiotensin II, which is correlated to hypertension." (PMID 30216974, 2018). "In the present study, 12-week-old SHR exhibited higher expression of inflammatory factors including TNF-α, IL-1β, IL-6, and iNOS at both mRNA and protein levels, which could be aggravated with the progress of hypertension and attenuated by captopril treatment." (PMID 30183974, 2018). "Furthermore, we found an interaction effect between central obesity and hypertension on circulatory TNF-α concentration." (PMID 29636702, 2018). "Finally, most studies about JYYS granule have been reported in Chinese, and JYYS granule had a therapeutic and protective effect on hypertension and early renal damage of hypertension by decreasing content of angiotensin II (AngII) and expression of TNF-α." (PMID 30598687, 2018). "Elevated levels of inflammatory cytokines, specifically TNF-α and IL-6, generate widespread dysfunction of the maternal vascular endothelium that could result in hypertension." (PMID 30079067, 2018). "Furthermore some researches proved that TNF-α protein is involved in Ang II signaling pathways, particularly by induced Ang II mediated hypertension." (PMID 29391930, 2017). "Furthermore, evidence from clinic investigations has showed that IFN-γ and TNF-α levels increased in hypertension patients compared with those in healthy subjects." (PMID 28757677, 2017). "We hypothesized that TNFα specifically in the kidney contributes to the development of hypertension and renal injury in Dahl salt-sensitive (SS) rats, a widely used model of human salt-sensitive hypertension and renal injury." (PMID 26916681, 2016). "Additionally, we observed TNF-α significantly upregulated in hypertension alone and the coexistence of hypertension and ovariectomy." (PMID 27929425, 2016). "Macrophages and lymphocytes infiltrate the interstitium in angiotensin II-induced hypertension, where T cells increase in the adventitia of blood vessels and secrete cytokines such as tumor necrosis factor-α (TNF-α) and IL-17 as well as NADPH oxidase, which then lead to elevated blood pressure." (PMID 27088098, 2016). "Likewise, the proinflammatory cytokines such as TNF-α are involved in the development and the maintenance of hypertension." (PMID 26783414, 2016). "It is well known that cytokines can manipulate cardiovascular system, like the roles played by TNF-α in the infectious shock, it has been hypothesized that cytokines may participate in the induction of hypertension." (PMID 28033321, 2016).
Hypertension (continued). "TNF-α have been shown to directly stimulate endothelial cells in culture to secrete endothelin 1 and cell adhesion molecules which would attract leukocytes to adhere to vascular tissues and play a role in edema and hypertension." (PMID 26113950, 2015). "To determine the effect of TLR4 blockade within the PVN on inflammatoy response in hypertension, we examined the levels of pro-inflammatory cytokines (PICs), TNF-α and IL-1β mRNA and protein levels in the PVN by real time RT PCR and western immunoblot, respectively." (PMID 25879545, 2015). "Here, we investigated whether HO-1 induction could attenuate TNF-α-induced hypertension in pregnant rats." (PMID 26347650, 2015). "Moreover, increased secretion of cytokines such as IFN-γ, IL-17A, and TNF-α by circulatory spleen-derived T cells was observed in Ang II-induced hypertension." (PMID 26504819, 2015). "In the present study, we have examined whether TNF-α contributes to Ang II-induced hypertension and adverse cardiac remodeling through oxidative stress and NF-κB mediated signaling." (PMID 26378790, 2015). "Therefore, blocking TNF-α is beneficial in preventing the cardiac fibrosis and remodeling induced by AngII-induced hypertension." (PMID 26378790, 2015). "The OR of hypertension might be different among duration of trial or type of different TNF inhibitor; we thus performed subgroup analysis according to duration of trial and TNF inhibitors type." (PMID 25860222, 2015). "Importantly, TNF-α-induced hypertension in pregnant rats is significantly attenuated by the AT1R antagonist losartan." (PMID 26569331, 2015). "Accordingly, thorough screening for subclinical hypertension of patients being considered for anti-TNF agent therapy and continuous monitoring may represent a therapeutic strategy to improve the safety of anti-TNF treatment that deserves further evaluation." (PMID 25860222, 2015). "Moreover, an inflammatory response in hypertension is characterized by a peripheral and central increase in various PICs, in particular, TNF-α and IL-1β." (PMID 25879545, 2015). "A recent study in patients suffering from aldosterone-producing adenomas and showing resistant arterial hypertension reported that they secreted significantly high levels of TNF-α, IL-6, and IL-1β from monocytes and IL-2, IFN-γ, and TNF-α from lymphocytes secreted at the beginning of the study." (PMID 26448944, 2015). "The association of TNF-α has been extensively reported in hypertension, but no previous study evaluated the effects of TNF-α on human endothelial cells." (PMID 26504819, 2015). "We have previously found that hypertension, hemodynamic stress, and cigarette smoke may activate TNF-α and induce phenotypic modulation in smooth muscle cells." (PMID 24739142, 2014). "As IL‐10 level is decreased in hypertensive conditions this may be primarily involved in the increased production of TNF‐α in many models of experimental hypertension such as ANG II‐dependent hypertensive rats and Dahl salt‐sensitive rats." (PMID 24744897, 2014). "We hypothesize that combined supplementation of micronutrients (folate and vitamin B12) and omega-3 fatty acids may reduce the inflammatory cytokine like tumor necrotic factor – alpha (TNF-α) in a rat model of pregnancy induced hypertension." (PMID 25405347, 2014). "A substantial production of NO has been shown to be induced by inflammation, where inflammatory cytokines such as TNF-α, IL-1β, and interferon-γ stimulate iNOS activity and may be responsible for hypertension and insulin." (PMID 24441717, 2014). "Additionally, serum HMW adiponectin significantly decreased, while TNFα greatly increased in hypertension patients as compared with healthy controls (2.32 ± 0.41 versus 5.24 ± 1.02 μg/mL, 3.30 ± 1.56 versus 2.34 ± 0.99 pg/mL, P < 0.05)." (PMID 24665369, 2014).